INS (insulin)
Diseases named in the same sentence as INS in open-access papers (continued):
Sharing a sentence is not in itself a finding about the gene and the disease.
diabetes (continued). "We conducted a cohort study of 28 900 UK patients with insulin-treated diabetes followed for 520 517 person-years, and compared their cancer incidence and mortality with national expectations." (PMID 15886700, 2005). "In fact, before the discovery of insulin, dietary carbohydrate restriction was the recommended treatment for diabetes management." (PMID 16018812, 2005). "In normal condition, insulin increases the receptor-mediated removal of LDL-cholesterol and decreased activity of insulin during diabetes causes hypercholestrolemia." (PMID 15969768, 2005). "According to these data, insulin sensitization through a PPAR-γ activation mechanism is effective in diabetes prevention." (PMID 16232315, 2005). "Many patients for whom diabetes medication is prescribed are poor compliers with treatment, including both oral medication and insulin." (PMID 15890071, 2005). "Health organizations have been slow to adapt carbohydrate restricted diets even in the face clear evidence for the adverse effects of high carbohydrate intake exacerbating the metabolic abnormalities in diabetes and insulin resistant states." (PMID 16018812, 2005). "Second, in studies among individuals with pancreatic cancer who underwent tumour resection, insulin sensitivity and diabetes status were reported as showing substantial improvement 3 months after surgery." (PMID 15886696, 2005). "MTHFR 677T allele carriers had an increased risk of PAD with an odds ratio of 3.54 (95% CI 1.01, 12.4), P = 0.049, after adjustment for age, sex, duration of diabetes, hypertension, current smoking habits, and use of insulin or oral treatment for diabetes." (PMID 16274479, 2005). "Liver, an insulin dependent tissue that plays a pivotal role in glucose and lipid homeostasis and it is severely affected during diabetes." (PMID 15969768, 2005). "Epidemiological studies indicate that the development of type 2 diabetes takes place over a long period of time from the initial decline of insulin effectiveness ultimately progressing to frank diabetes when β-cell function collapses." (PMID 16232315, 2005). "The most striking, and unexpected, finding of our study was the highly significant excess of ovarian cancer in women with insulin-treated diabetes diagnosed at young ages (i.e. those who presumptively had type I diabetes)." (PMID 15886700, 2005). "We examined cancer risks in a UK cohort of 28 900 patients with insulin-treated diabetes of known date of diagnosis, most aged under 30 years at diagnosis of diabetes and therefore probably with type I diabetes." (PMID 15886700, 2005). "Results of the mixed effects model showed that patients who were uninsured, had diabetes for a longer period of time, used insulin or multiple oral agents, or had high cholesterol had higher A1C values over time indicating poorer glycemic control." (PMID 15833140, 2005). "Patients had a mean age of 55 years, 69% were female, the mean duration of diabetes was 7.1 years, 31% were treated with insulin, and 57% were obese." (PMID 15833140, 2005). "With regards to growth factor deficiency, insulin has a vasodilatory effect that is dependent on CGRP release, which is compromised in diabetes." (PMID 15857517, 2005). "We assessed possible interactions between cadmium and blood lead, diabetes (insulin-treated vs. the rest), hypertension, or use of NSAIDs, and between blood lead and diabetes, hypertension, or use of NSAIDs." (PMID 16263522, 2005). "Over a two-week period, while her parents were attending a diabetes education program, her glycemic levels became normalized by means of human pre-mixture (80N/20R) insulin before breakfast and supper (0.9 units/kg/day)." (PMID 15947838, 2005). "Intensive diabetes management is most appropriate for people willing and able to monitor their blood glucose frequently throughout the day and adjust their insulin, food intake, and physical activity based on blood glucose test results." (PMID 16263044, 2005).
diabetes (continued). "In particular, immunization withinsulin peptide B:9-23 can be used to induce insulin autoantibodies and diabetesin animal models or used to prevent diabetes." (PMID 16295523, 2005). "Compliance with these lifestyle modifications is less than satisfactory, however, and a high carbohydrate diet raises postprandial plasma glucose and insulin secretion, thereby increasing risk of CVD, hypertension, dyslipidemia, obesity and diabetes." (PMID 16018812, 2005). "Impaired β-cell function predicts future diabetes, and work from our laboratory and others suggest that the ability of the pancreatic β-cell to compensate for prevailing insulin sensitivity (ie, β-cell compensation) is highly heritable." (PMID 16229747, 2005). "With the advent of insulin, the prognosis changed overnight, and we have continued to witness improvements in diabetes care and outcomes." (PMID 15630467, 2004). "Meanwhile, IGFBP-1 expression can be dynamically regulated by nutritional status, increasing during fasting, malnutrition and diabetes but decreasing upon re-feeding or insulin treatment." (PMID 15350195, 2004). "Eight of the ten items of the Impact-Self subscale clearly relate to the effects of diabetes and its treatment on the individual (domains of insulin, bleed, finger tests, moody, unwell, wake nights, high BG and low BG." (PMID 15535888, 2004). "Pancreatic islet transplant has offered renewed hope to many patients with diabetes, who envision a life free of glucose checks and insulin injections." (PMID 15630467, 2004). "It is known that defects in insulin signaling pathway leads to pathological conditions like diabetes, wherein normal or elevated levels of insulin produces impaired biological response." (PMID 15291972, 2004). "Simulation results indicate that, the alterations in binding constant of allosteric interactions and Michaelis-Menten constants in modification-demodification cycles in the insulin-signaling pathway can result in insulin resistance or diabetes." (PMID 15291972, 2004). "In the management part, as metabolic control of diabetes improves leukocyte functions and overall immune status of patient so insulin was started and dose was adjusted to achieve good metabolic control." (PMID 15575957, 2004). "Agents that mimic the physiological processes that are regulated by insulin have the potential to be of therapeutic value for the treatment of insulin resistant states such as diabetes." (PMID 15350195, 2004). "Banting and Best's discovery of insulin in the early 1920s revolutionized diabetes treatment and greatly improved the prognosis for what had previously been a rapidly fatal disease." (PMID 15630467, 2004). "Long-term hyperlipidemia is known to induce frank diabetes with impaired release of insulin, in contrast to short-term, high-fat feeding, which increases release of insulin, but impairs the response to it." (PMID 15523558, 2004). "Most people with diabetes can, with diligence and perseverance, implement an insulin regimen that maintains tight glucose control while avoiding dangerous hypoglycemia." (PMID 15630467, 2004). "Do you ever find you need to fit diabetes into your social life, like carrying equipment, planning when to eat, or where to take insulin when away from home?" (PMID 15535888, 2004). "Islet transplantation offers hope to many patients with diabetes, who envision a life free of glucose checks and insulin injections." (PMID 15630467, 2004). "As the polymorphism at +1127 INS-PstI and its tightly linked VNTR have been reported to be associated with diabetes, we first stratified the analysis by diabetes status, which was based on self-report." (PMID 12610512, 2003). "Wild bank voles (Clethrionomys glareolus) kept in the laboratory under barren housing conditions develop high incidences of type 1 diabetes mellitus due to beta cell– specific lysis in association with the appearance of GAD65, IA-2, and insulin autoantibodies." (PMID 12745667, 2003).
diabetes (continued). "We examined 35 genes predicted to have their major influence on insulin action, and three (9%)—INSR, PIK3R1, and SOS1—showed significant associations with diabetes." (PMID 14551916, 2003). "The use of vitamin A togetherwith insulin provides a better metabolic controland more benefits than use of insulin alone inthe reduction of diabetes-induced vascularcomplications." (PMID 11991198, 2002). "Our raw data consisted of 909 consumer terms (eg, borderline diabetes, sugar dibetes, suger diabetes) and 938 physician terms (eg, insulin insensitivity and diabetic flow sheet)." (PMID 11720966, 2001). "Fenugreek (Trigonella foenum-graecum L. seed) is afood with traditional medicinal use in diabetes.Beneficial effects have been demonstrated in diabeticanimals and both insulin-dependent andnon-insulin-dependent diabetic subjects." (PMID 12369721, 2001). "(For more information on diabetes and on alcohol’s effects on insulin, glucagon, and the management of diabetes, see the article by Emanuele and colleagues, pp." (PMID 15706790, 1998). "Accordingly, disturbances of that balance, such as an insulin deficiency or an inability of the body to respond adequately to insulin, result in serious disorders, such as diabetes mellitus." (PMID 15706790, 1998). "As EAT is strongly associated with inflammation in the setting of obesity and diabetes, the reduction in EAT observed here may have also decreased inflammation, and subsequently improved insulin sensitivity." (PMID 41251158, 2026). "The North American CFRD Guidelines Committee endorses OGTT over fasting BGL and HbA1c because of its superior accuracy, its association with nutritional and pulmonary deterioration, and its ability to facilitate early insulin treatment to prevent CF‐ and diabetes‐related complications." (PMID 41552835, 2026). "In diabetes, dysfunctional autophagy leads to the accumulation of damaged mitochondria and endoplasmic reticulum (ER) in β-cells, triggering oxidative stress and ER stress and ultimately promoting β-cell apoptosis and insulin secretion defects." (PMID 41601937, 2026). "The diabetes is insulin-dependent from birth due to critical β-cell mass reduction." (PMID 41614934, 2026). "The administration of pharmacological doses of oral thiamine utilizes low-affinity transporters to restore intracellular levels, which can correct the megaloblastic anemia and significantly improve diabetes control, potentially eliminating the need for insulin in the early stages of the disease." (PMID 41614934, 2026). "Insulin use selects for individuals with poor glycemic control and thus may introduce significant variation in severity of diabetes." (PMID 41583363, 2026). "We describe a 14-year-old girl with long-standing poorly controlled type 1 diabetes mellitus (HbA1c 15.1%) who, the week following recovery from severe diabetic ketoacidosis and a rapid increase in insulin therapy, experienced acute edema and gained seven kilos of weight over the next week." (PMID 41640926, 2026). "In diabetics, tirzepatide has been found to reduce the need for insulin, but once exogenous insulin delivery is not enough, relative insulin deficiency results in accelerated ketogenesis." (PMID 41584389, 2026). "The patient also had a drug history of Insulin for 10 years for the management of diabetes." (PMID 41497060, 2026). "In addition, weight loss, including fat mass reduction, after exercise can help improve insulin sensitivity, hyperglycemia, or blood pressure in people with obesity or diabetes." (PMID 41523744, 2026). "Because insulin is a central regulator of glucose homeostasis, molecules that influence its secretion, sensitivity, or signaling pathways have emerged as major focal points in contemporary diabetes research." (PMID 41599361, 2026).
diabetes (continued). "After adjusting for HbA1c, BMI, and diabetes duration, patients on insulin therapy (22.8 ± 1.5 ng/mL) showed significantly higher NOX2 levels compared to those on metformin alone (19.8 ± 0.9 ng/mL, p = 0.041) or DPP-4 inhibitors alone (18.9 ± 1.2 ng/mL, p = 0.028)." (PMID 41607455, 2026). "Additionally, the lack of propensity score matching, confounder adjustment, or multivariate regression prevents adequate control of baseline differences, including BMI, diabetes duration, insulin use, and comorbidities." (PMID 41601512, 2026). "Of the many islet-related gene variants linked to random (i.e., non-fasting) blood glucose and diabetes, a number of them influence the biosynthesis and trafficking of proinsulin, including the INS gene itself." (PMID 41516356, 2026). "Pioglitazone enhances insulin sensitivity in patients with type 2 diabetes mellitus, but its impact on glycation remains unclear." (PMID 42123882, 2026). "Although nutritional management is crucial for success, generic guidelines often do not provide the required differentiation for various diabetes causes and contemporary insulin delivery methods." (PMID 41971384, 2026). "Eight variables were significantly associated with hypoglycemia: diabetic peripheral neuropathy, creatinine (Cr), indirect bilirubin (IB), triglycerides (TGs), use of antibiotics within 48 h of admission, duration of diabetes, insulin dosage, and body mass index (BMI)." (PMID 41992707, 2026). "When HRD1 is unavailable, misfolded proinsulin accumulates, accompanied by increased phospho-eIF2α that limits further proinsulin synthesis, plus ΣR1-dependent autophagy activation, ultimately lowering steady-state β cell proinsulin (and insulin) levels and triggering diabetes." (PMID 41252202, 2026). "Third, we lack detailed information about diabetes-specific factors that might influence outcomes, such as glycemic control, diabetes duration, insulin requirements, and diabetic microvascular complications." (PMID 41602323, 2026). "In preclinical models, PAHSA treatment improves glucose tolerance, enhances insulin signaling, and lowers inflammatory markers, suggesting that these lipids may help prevent or reverse pancreatic β-cell dysfunction in diabetes." (PMID 41189469, 2026). "Unexpectedly, these mice also developed insulin-dependent diabetes mellitus, as indicated by reduced insulin and C-peptide levels, decreased pancreatic β cell mass, impaired glucose-stimulated insulin secretion, and elevated fasting blood glucose, even in the absence of a high-fat diet." (PMID 41480757, 2026). "Indeed, in the setting of diminished insulin storage in β cells, serum insulin cannot keep up with demand, leading to diabetes." (PMID 41252202, 2026). "The interaction between glucose and insulin is crucial to developing diabetes treatment strategies." (PMID 41551260, 2026). "Diabetes is characterised by elevated plasma glucose and diminished efficacy of insulin." (PMID 41590669, 2026). "Overall, insulin icodec represents an important advancement in diabetes care, with the potential to simplify insulin regimens and improve patient-centered outcomes, although further studies are warranted to evaluate long-term safety and broader clinical applications." (PMID 42254168, 2026). "HbA1c levels were observed as positively associated with the purchase of diabetes medications for both insulin and non-insulin." (PMID 39643847, 2026). "Furthermore, we showed that SGLT2 inhibitor exerted more stronger effects on insulin biosynthesis and β-cell mass when they were used at an early stage of diabetes." (PMID 41585322, 2026). "The mean duration of diabetes was 5.4 ± 0.4 years, and 24% of the patients were insulin dependent." (PMID 42005659, 2026).
diabetes (continued). "High quality, context‐specific research is urgently needed to answer questions about stakeholder experience of biosimilar insulin switches and support healthcare systems to effectively balance the needs of individual patients with diabetes and the need to make financial efficiencies." (PMID 41466553, 2026). "However, other studies reported that insulin users tend to have better diabetes knowledge, most likely due to more frequent healthcare interactions." (PMID 41311517, 2026). "In contrast, among participants with T2D, insulin treatment emerged as the strongest independent predictor of engagement (β = 0.996, 95% CI 0.859-1.134, p < 0.001), and diabetes-related stress emerged as an independent predictor of engagement (β = 0.069, 95% CI 0.006-0.132, p = 0.033)." (PMID 41897253, 2026). "Type 2 diabetes mellitus (T2DM) is defined as a constellation of metabolic abnormalities marked by persistently elevated blood glucose levels resulting from reduced pancreatic insulin secretion and/ or decreased insulin sensitivity." (PMID 41525345, 2026). "The resulting impairment of insulin signaling may further amplify systemic inflammation and contribute to OA pathogenesis among individuals with diabetes or hypertension." (PMID 41607949, 2026). "Type 2 diabetes mellitus (T2DM) is primarily characterised by insulin resistance accompanied by an inadequate compensatory insulin response, which arises from impairments in insulin signalling pathways and subsequent disturbances in glucose and lipid metabolism." (PMID 41549047, 2026). "The diabetes is insulin-dependent from birth due to the critical reduction in β-cell mass." (PMID 41614934, 2026). "Early intervention with non‐insulin antihyperglycemic medications for control of new‐onset prediabetes/diabetes may be crucial in preventing the need for insulin prescription and worsening of survival." (PMID 41287203, 2026). "Because diabetes is marked by chronic low‐grade inflammation and impaired insulin signaling, the markedly lower CTRP12 levels observed in diabetic CAD patients may reflect a greater inflammatory and metabolic burden." (PMID 41524288, 2026). "Therefore, enhancing diabetes education, especially for those on complex regimens like insulin, is a key to improving patient-reported outcomes." (PMID 41311517, 2026). "Current consensus from the American Diabetes Association (ADA) and the European Association for the Study of Diabetes (EASD) recommends combination therapy for patients with HbA1c levels exceeding 8.5%, and insulin based therapy when HbA1c levels above 10%." (PMID 41521023, 2026). "While the canonical insulin pathway (PI3K/Akt/TBC1D4) is the most potent and specific mechanism in the postprandial state, its dysfunction is centrally associated with insulin resistance and type 2 diabetes mellitus (T2DM)." (PMID 42074118, 2026). "This case may represent one of the early reports describing the successful management of capivasertib-induced diabetes with insulin-independent glucose-lowering agents, suggesting a potential strategy for managing AKT inhibitor-induced hyperglycemia." (PMID 42022705, 2026). "Additionally, it discusses special situations such as intravenous insulin therapy, concomitant therapy with glucocorticoids and use of diabetes technology during hospitalization and the perioperative setting." (PMID 42162480, 2026). "Finally, we address translational challenges and future perspectives, highlighting the role of needle-free insulin delivery as a patient-centered strategy to improve adherence and metabolic control in diabetes care." (PMID 41900895, 2026). "Insulin therapy remains essential for the management of diabetes mellitus; however, conventional subcutaneous injection continues to impose significant physical, psychological, and behavioral barriers that negatively affect treatment adherence and metabolic outcomes." (PMID 41900895, 2026).